CYP21A2 (cytochrome P450 family 21 subfamily A member 2)
Description:
A cytochrome P450 monooxygenase that plays a major role in adrenal steroidogenesis. Catalyzes the hydroxylation at C-21 of progesterone and 17alpha-hydroxyprogesterone to respectively form 11-deoxycorticosterone and 11-deoxycortisol, intermediate metabolites in the biosynthetic pathway of mineralocorticoids and glucocorticoids. Mechanistically, uses molecular oxygen inserting one oxygen atom into a substrate, and reducing the second into a water molecule, with two electrons provided by NADPH via cytochrome P450 reductase (CPR; NADPH-ferrihemoprotein reductase).
Synonyms: CYP21; CYP21B; P450c21B; CA21H; CPS1; CAH1
Tractability: Small molecule: a structure with a bound ligand is known; a high-quality ligand is known; it belongs to a druggable protein family. Antibody: UniProt places it where antibodies can reach, with high confidence. PROTAC: a small molecule that binds it is known.
Target class: Cytochrome P450 family 21; Cytochrome P450 21A2; Enzyme; Cytochrome P450 family 21A; Cytochrome P450
Gene: Protein-coding gene on chromosome 6 (32,038,298 to 32,042,321, forward strand). Ensembl gene ENSG00000231852.
Subcellular location: Endoplasmic reticulum membrane; Microsome membrane
Pathways (Reactome):
Metabolism: Endogenous sterols; Glucocorticoid biosynthesis; Mineralocorticoid biosynthesis
Disease: Defective CYP21A2 causes AH3
Gene Ontology:
Molecular function: 17-hydroxyprogesterone 21-hydroxylase activity; heme binding; progesterone 21-hydroxylase activity; steroid hydroxylase activity; steroid 21-monooxygenase activity; iron ion binding; monooxygenase activity; oxidoreductase activity, acting on paired donors, with incorporation or reduction of molecular oxygen
Biological process: cortisol biosynthetic process; steroid biosynthetic process; steroid metabolic process; glucocorticoid biosynthetic process; mineralocorticoid biosynthetic process; sterol metabolic process; ketone metabolic process; olefinic compound metabolic process; primary alcohol metabolic process
Cellular component: endoplasmic reticulum membrane
Genetic constraint (gnomAD): Loss-of-function variants: 24 observed, 37.09 expected, observed/expected ratio (o/e) 0.65, 90% interval 0.47 to 0.91. The synonymous counts are far from expectation, so gnomAD's model fits this gene poorly and the ratio says little. Missense variants: 336 observed, 439.9 expected, observed/expected ratio (o/e) 0.76, 90% interval 0.7 to 0.84. Synonymous variants: 124 observed, 173.88 expected, observed/expected ratio (o/e) 0.71, 90% interval 0.62 to 0.83.
Homologues: Orthologues: macaque CYP21A2 (80% identical), pig CYP21A2 (79% identical), rabbit CYP21A2 (79% identical), dog CYP21A2 (78% identical), mouse Cyp21a1 (71% identical), rat Cyp21a1 (69% identical), zebrafish cyp21a2 (40% identical).
Diseases named in the same sentence as CYP21A2 in open-access papers:
CYP21A2 is named in the same sentence as 92 diseases in open-access papers, as found by Europe PMC text mining. Sharing a sentence is not in itself a finding about the gene and the disease. The quoted sentences say what the papers report.
congenital adrenal hyperplasia (155 papers, 2009 to 2026). Congenital adrenal hyperplasia (CAH) is an inherited endocrine disorder caused by a steroidogenic enzyme deficiency that is characterized by adrenal insufficiency and variable degrees of hyper or hypo androgyny manifestations, depending of the type and the severity of the disease. "CYP21A2 gene, associated with congenital adrenal hyperplasia due to 21-hydroxylase deficiency, showed a lower carrier frequency of 1:19, compared with a NFE population estimate of 1:17." (PMID 41303398, 2025). "21-hydroxylase deficiency (21OHD)(OMIM: 201910) is an autosomal recessive disorder caused by pathogenic variants in the CYP21A2 gene, accounting for over 90% of congenital adrenal hyperplasia (CAH) cases." (PMID 41180189, 2025). "The most frequently affected gene was CYP21A2, involved in congenital adrenal hyperplasia due to 21-hydroxylase deficiency, observed in three independent patients." (PMID 40282394, 2025). "Mutations in CYP21A2 are well-known causes of human autosomal recessive disorders of adrenal steroidogenesis, known as congenital adrenal hyperplasia (CAH), resulting from 21-hydroxylase deficiency." (PMID 41300825, 2025). "CYP21A2 (cytochrome P450 family 21 subfamily A member 2) is associated with congenital adrenal hyperplasia due to 21-hydroxylase deficiency." (PMID 40428427, 2025). "Congenital adrenal hyperplasia (CAH) is a group of autosomal recessive disorders due to mutations in CYP21A2 gene leading to enzyme deficiencies involved in steroid hormone synthesis in adrenal glands." (PMID 40149462, 2025). "Congenital adrenal hyperplasia due to 21-hydroxylase deficiency is the most common subtype and mainly resulted from CYP21A2 variants." (PMID 40136637, 2025). "For example, in Taiwan’s newborn screening program, funded by the National Health Insurance, the pathogenic gene for congenital adrenal hyperplasia (CYP21A2) has a pseudogene, CYP21A1P, which increases the risk of diagnostic error." (PMID 41329681, 2025). "The major clinical entities included Congenital Adrenal Hyperplasia (CAH) due to pathogenic variants in CYP21A2 gene and Multiple Endocrine Neoplasia (MEN) type 2 due to pathogenic variants in the RET proto-oncogene." (PMID 38637882, 2024). "Another example is the p.T450P amino acid exchange in CYP21A2, which results in a loss of 17-hydroxyprogesterone clearance in vitro and is associated with congenital adrenal hyperplasia due to 21-hydroxylase deficiency." (PMID 38802404, 2024). "An accumulation of 17-hydroxyprogesterone and 21-deoxycortisol can be seen in congenital adrenal hyperplasia, caused by a hereditary dysfunction of 21-hydroxlase (CYP21A2)." (PMID 38966215, 2024). "CYP21A2 deficiency in humans leads to congenital adrenal hyperplasia, manifested by corticosteroid deficiency, secondary hyper-androgens, and even pseudohermaphroditism in women." (PMID 39457878, 2024). "Congenital adrenal hyperplasia (CAH) caused by mutations in CYP21A2 results in reduced activity of 21-hydroxylase, an enzyme essential to the synthesis of aldosterone and cortisol." (PMID 37850096, 2023). "Genetic diversity of mutations in the CYP21A2 gene is the main cause of the monogenic congenital adrenal hyperplasia (CAH) disorder." (PMID 36264454, 2023). "CAH-X is a hypermobility-type Ehlers–Danlos syndrome connective tissue dysplasia affecting approximately 15% of patients with 21-hydroxylase deficiency (21-OHD) congenital adrenal hyperplasia (CAH) due to contiguous deletion of CYP21A2 and TNXB genes." (PMID 36833192, 2023). "Congenital adrenal hyperplasia due to 21-hydroxylase deficiency is an autosomal recessive disorder caused by CYP21A2 gene mutations, and its molecular diagnosis is widely used in clinical practice to confirm the hormonal diagnosis." (PMID 37011374, 2023).
congenital adrenal hyperplasia (continued). "One patient had RFXANK pathogenic variant associated with a pathogenic variant in CYP21A2 gene causing congenital adrenal hyperplasia; thus, a specialist was involved in the patient management plan." (PMID 35482138, 2022). "The most common presentation of 46,XX DSD is congenital adrenal hyperplasia (CAH) that is caused by pathogenic variants in the CYP21A2 gene." (PMID 35432193, 2022). "Congenital adrenal hyperplasia (CAH) with 21-hydroxylase deficiency (21-OHD) deficiency is an autosomal recessive disorder caused by mutations in the CYP21A2 gene, and is considered one of the most common causes of genital ambiguity." (PMID 36242011, 2022). "The aim of this study was to characterize CYP21A2 gene variants in adult patients with classical congenital adrenal hyperplasia (CCAH) from southern Poland and to analyze genotype-phenotype correlations." (PMID 35079965, 2022). "CYP21A2 contributes to the steroidogenesis of adrenal glands, and its mutations cause congenital adrenal hyperplasia (CAH)." (PMID 36454796, 2022). "Deficiency of 21-hydroxylase enzyme (CYP21A2) represents 90% of cases in congenital adrenal hyperplasia (CAH), an autosomal recessive disease caused by defects in cortisol biosynthesis." (PMID 35008721, 2021). "Congenital adrenal hyperplasia (CAH) is a genetic disorder caused by mutations in the CYP21A2 gene, resulting in a defective 21-hydroxylase enzyme necessary to produce cortisol and aldosterone." (PMID 32869847, 2020). "Congenital adrenal hyperplasia (CAH) is in more than 95% of cases due to 21-hydroxylase deficiency (21OHD) caused by mutations in the CYP21A2 gene." (PMID 33239597, 2020). "Congenital adrenal hyperplasia (CAH) is most commonly caused by mutations in the CYP21A2 gene (resulting in 21-hydroxylase deficiency, 21OHD) and has a prevalence of 1:15.000 in most populations." (PMID 31927590, 2020). "The CYP21A2 gene, which encodes a steroid 21-hydroxylase, is known as a gene associated with congenital adrenal hyperplasia, and very little is known about it in BC." (PMID 31569550, 2019). "Congenital adrenal hyperplasia due to 21-hydroxylase deficiency is an autosomal recessive disorder caused by mutations in the CYP21A2 gene." (PMID 31001504, 2019). "Congenital adrenal hyperplasia (CAH) (OMIM #201910) is a complex disease most often caused by pathogenic variant of the CYP21A2 gene." (PMID 30816000, 2019). "The simple virilizing (SV) form of congenital adrenal hyperplasia (CAH) is an autosomal recessive disorder usually caused by steroid 21-hydroxylase deficiency due to I172N missense mutation at the CYP21A2 gene." (PMID 31217034, 2019). "The promoter methylation of KCNH2 and CYP21A2 genes, which are known as a regulator of apoptosis and associated adrenal hyperplasia, was measured by BSC in the three pairs of CMTs and adjacent normal samples." (PMID 31569550, 2019). "Mutations of the CYP21A2 gene encoding 21-hydroxylase (21-OH) cause congenital adrenal hyperplasia (CAH), an autosomal recessive disorder of steroidogenesis." (PMID 31666125, 2019). "More than 95% of congenital adrenal hyperplasia cases are due to mutations in CYP21A2, the gene encoding the adrenal steroid 21-hydroxylase enzyme (P450c21)." (PMID 31708872, 2019). "Steroid 21-hydroxylase deficiency due to CYP21A2 gene mutations, including p.Gln319*, is seen in more than 90% of all congenital adrenal hyperplasia cases." (PMID 30833958, 2019). "The most common form of congenital adrenal hyperplasia is 21-hydroxylase deficiency (CAH) due to mutations in the active gene CYP21A2." (PMID 30470203, 2018). "Congenital Adrenal Hyperplasia is an autosomal recessive disordermainly caused by defects in 21-Hydroxylase gene (CYP21A2) which codes for21-Hydroxylase enzyme." (PMID 28275658, 2017). "Mutations in CYP21A2 are the main cause of the autosomal recessive disorder congenital adrenal hyperplasia (CAH)." (PMID 24671123, 2014).
congenital adrenal hyperplasia (continued). "Congenital adrenal hyperplasia (CAH) is a group of autosomal recessive disorders caused by defects in the steroid 21 hydroxylase gene (CYP21A2)." (PMID 21329531, 2011). "Congenital adrenal hyperplasia due to 21-hydroxylase deficiency is caused by deletions, large gene conversions or mutations in CYP21A2 gene." (PMID 20587039, 2010). "More than 90% of Congenital Adrenal Hyperplasia (CAH) cases are associated with mutations in the 21-hydroxylase gene (CYP21A2) in the HLA class III area on the short arm of chromosome 6p21.3." (PMID 19624807, 2009). "Congenital Adrenal Hyperplasia (CAH) is an autosomal recessive disorder mainly caused by defects in the steroid 21-hydroxylase gene (CYP21A2)." (PMID 19624807, 2009). "In conclusion, our case may provide insights into the phenotype associated with the c.738+75C>T mutation in the CYP21A2 gene, which is suggested to be linked to the salt-wasting form of congenital adrenal hyperplasia." (PMID 40724898, 2025). "Congenital adrenal hyperplasia (CAH) due to 21-hydroxylase deficiency (21-OHD) caused by pathological variants in the CYP21A2 gene has been classified into a) the classical form that includes the severe salt-wasting (SW) and milder simple-virilizing (SV) forms and b) the non-classical (NC) form." (PMID 37324261, 2023). "Accordingly, having guidelines for the carrier screening of congenital adrenal hyperplasia and preconception and prenatal screening programs for CYP21A2 mutations seems to be the requisite in Northern Cyprus considering the preventive medicine strategies on the island." (PMID 37895316, 2023). "Aim of the present study is to evaluate whether genomic variants in POR contribute to the phenotype of patients with congenital adrenal hyperplasia due to CYP21A2 mutations." (PMID 33666875, 2021). "Indeed, CYP21A2 alterations are responsible for congenital adrenal hyperplasia, caused by diminished aldosterone and cortisol production that result in ambiguous genitalia in female affected." (PMID 34803902, 2021). "In congenital adrenal hyperplasia, mutations in the CYP21A2 gene can cause varying degrees of 21-hydroxylase activity loss leading to a range of phenotypes (from androgen excess for the milder form to virilization or “salt-wasting” with cortisol and mineralocorticoid deficiency for the most severe)." (PMID 34034803, 2021). "The non-allelic gene conversion in the background of the concerted evolution of CYP21 paralogues is well studied in humans, because congenital adrenal hyperplasia (CAH), a frequent Mendelian disorder mostly caused by gene conversion from CYP21A1P to CYP21A2, is a focus of human geneticists." (PMID 24312389, 2013). "Congenital adrenal hyperplasia (CAH) is caused by variants in the CYP21A2 gene and subsequently results in 21-hydroxylase deficiency." (PMID 41988147, 2026). "Congenital adrenal hyperplasia (CAH) due to 21-hydroxylase deficiency (21-OHD CAH) is an autosomal recessive genetic condition that results from pathogenic variants in the CYP21A2 gene." (PMID 42256322, 2026). "Congenital adrenal hyperplasia (CAH) caused by 21-hydroxylase deficiency (21OHD), resulting from mutations in the CYP21A2 gene, is an autosomal recessive condition that requires lifelong treatment and impacts the quality of life." (PMID 39997713, 2025). "21‐hydroxylase deficiency (21‐OHD) represents the most common form of congenital adrenal hyperplasia (CAH) caused by pathogenic variants in the CYP21A2 gene." (PMID 41438257, 2025). "A notable example is Patient P10-B4, who was diagnosed with congenital adrenal hyperplasia (CAH) caused by an SNP in intron 2 of the CYP21A2 gene." (PMID 41561440, 2025). "Background/Objectives: Congenital adrenal hyperplasia (CAH) is an autosomal recessive disorder caused by mutations in the CYP21A2 gene associated with 21-hydroxylase deficiency and increased levels of adrenal androgens." (PMID 40149462, 2025).
congenital adrenal hyperplasia (continued). "Congenital adrenal hyperplasia (CAH) is caused by mutations in the CYP21A2 gene, which leads to reduced enzymatic activity in the steroidogenesis pathway." (PMID 39062040, 2024). "Congenital adrenal hyperplasia (CAH) is a group of autosomal recessive disorders caused by pathogenic variants identified in seven genes (CYP21A2, CYP11B1, CYP17A1, HSD3B2, StAR, POR, and CYP11A1) involved in the steroidogenesis pathway." (PMID 39451515, 2024). "21-hydroxylase deficiency (21-OHD) represents the most common form of congenital adrenal hyperplasia (CAH) due to CYP21A2 gene pathogenic variants." (PMID 39451515, 2024). "Congenital adrenal hyperplasia (CAH) owing to 21-hydroxylase deficiency (21-OHD) is a rare autosomal recessive disorder caused by pathological variants in the CYP21A2 gene." (PMID 37324261, 2023). "In congenital adrenal hyperplasia (CAH), the majority of affected individuals display mutations in the 21-hydroxylase (CYP21A2) gene." (PMID 35148399, 2022). "The CYP21A2 deficiency represents about 95% of cases in congenital adrenal hyperplasia (CAH), a group of enzymatic disorders that affect cortisol biosynthesis." (PMID 36278220, 2022). "CYP21A2 deficiency represents 95% of congenital adrenal hyperplasia (CAH) cases, a group of genetic disorders that affect steroid biosynthesis." (PMID 36278220, 2022). "This review provides an overview on RCCX complexity pointing out the molecular bases of Congenital Adrenal Hyperplasia (CAH) due to CYP21A2 deficiency, CAH-X Syndrome and disorders related to CNV of complement component C4." (PMID 34394006, 2021). "Mutations in CYP21A2 can lead to 21-hydroxylase deficiency, and congenital adrenal hyperplasia (CAH) displayed early puberty." (PMID 34438721, 2021). "Congenital adrenal hyperplasia (CAH) is mainly caused by mutations in the CYP21A2 gene, resulting in impaired production of cortisol and aldosterone in the adrenal cortex." (PMID 32497228, 2020). "Tenascin-X (TNX) is a large extracellular matrix protein discovered because its TNXB gene overlaps the CYP21A2 gene encoding steroid 21-hydroxylase (P450c21), whose mutations cause congenital adrenal hyperplasia (CAH)." (PMID 33505400, 2020). "Classical congenital adrenal hyperplasia (CAH) caused by pathogenic variants in the steroid 21-hydroxylase gene (CYP21A2) is a severe life-threatening condition." (PMID 32824094, 2020). "Approximately 10% of patients with congenital adrenal hyperplasia (CAH) due to 21-hydroxylase deficiency carry a mutation that disrupts CYP21A2 and the flanking TNXB gene resulting in CAH-X, a contiguous gene deletion syndrome." (PMID 31666125, 2019). "This study was performed to analyze the mutational spectrum of the CYP21A2 gene in Congenital adrenal hyperplasia (CAH) patients in Guangxi China, to identify mutational hot spots and to determine the correlation between the genotypes and phenotypes of CAH." (PMID 33072985, 2019). "Congenital adrenal hyperplasia (CAH) is a genetic disorder in which adrenocortical steroid synthesis is impaired due to a deficiency in particular steroidogenic enzymes, most often steroid 21-hydroxylase (CYP21A2)." (PMID 29038332, 2017). "In about 95% of cases, congenital adrenal hyperplasia (CAH) is caused by mutations in CYP21A2 gene encoding steroid 21-hydroxylase (21OH)." (PMID 24671123, 2014). "21-Hydroxylase deficiency (21-OHD) is the most common cause of congenital adrenal hyperplasia (CAH), caused by sequence variants in the 21-hydroxylase gene (CYP21A2)." (PMID 23484098, 2013). "Congenital adrenal hyperplasia (CAH) is usually caused by the deficiency of the 21-hydroxylase enzyme encoded by the CYP21A2 gene." (PMID 23896598, 2013).